Y_RNA (Y RNA )
Gene: Miscellaneous RNA gene on chromosome 9 (71,902,455 to 71,902,550, reverse strand). Ensembl gene ENSG00000200922.
Homologues: Orthologues: chimpanzee Y_RNA (99% identical). Paralogues in human: Y_RNA (83% identical), Y_RNA (82% identical), RNY3 (81% identical), RNY3P1 (81% identical), Y_RNA (81% identical), Y_RNA (80% identical), Y_RNA (79% identical), RNY3P11 (78% identical), Y_RNA (78% identical), RNY3P14 (77% identical), RNY3P16 (77% identical), Y_RNA (77% identical), and 88 more.